STAM (signal transducing adaptor molecule)
Description:
Involved in intracellular signal transduction mediated by cytokines and growth factors. Upon IL-2 and GM-CSL stimulation, it plays a role in signaling leading to DNA synthesis and MYC induction. May also play a role in T-cell development. Involved in down-regulation of receptor tyrosine kinase via multivesicular body (MVBs) when complexed with HGS (ESCRT-0 complex). The ESCRT-0 complex binds ubiquitin and acts as a sorting machinery that recognizes ubiquitinated receptors and transfers them to further sequential lysosomal sorting/trafficking processes. (Microbial infection) Plays an important role in Dengue virus entry.
Synonyms: STAM-1; STAM1
Tractability: Antibody: UniProt places it where antibodies can reach, with high confidence. PROTAC: UniProt records ubiquitination sites on it; ubiquitination databases record sites on it; its protein half-life has been measured.
Gene: Protein-coding gene on chromosome 10 (17,644,124 to 17,716,824, forward strand). Ensembl gene ENSG00000136738.
Subcellular location: Cytoplasm; Early endosome membrane
Subcellular location (Human Protein Atlas): Vesicles
Pathways (Reactome):
Signal Transduction: EGFR downregulation; Negative regulation of MET activity; RHOU GTPase cycle
Vesicle-mediated transport: Cargo recognition for clathrin-mediated endocytosis; Clathrin-mediated endocytosis; Endosomal Sorting Complex Required For Transport (ESCRT)
Disease: InlB-mediated entry of Listeria monocytogenes into host cell
Metabolism of proteins: Metalloprotease DUBs
Gene Ontology:
Molecular function: protein binding; ubiquitin-like protein ligase binding; phosphatidylinositol binding; ubiquitin binding
Biological process: positive regulation of exosomal secretion; regulation of extracellular exosome assembly; macroautophagy; membrane fission; multivesicular body assembly; protein transport to vacuole involved in ubiquitin-dependent protein catabolic process via the multivesicular body sorting pathway; signal transduction
Cellular component: early endosome membrane; ESCRT-0 complex; cytosol; cytoplasm
Genetic constraint (gnomAD): Loss-of-function variants: 18 observed, 53.59 expected, observed/expected ratio (o/e) 0.34, 90% interval 0.23 to 0.5. The upper end of that interval is the gene's LOEUF score, 0.5, which puts it in group 2 of 6, group 1 being the genes least tolerant of losing a copy. Missense variants: 568 observed, 600.67 expected, observed/expected ratio (o/e) 0.95, 90% interval 0.88 to 1.01. Synonymous variants: 217 observed, 208.84 expected, observed/expected ratio (o/e) 1.04, 90% interval 0.93 to 1.16.
Homologues: Orthologues: chimpanzee STAM (99% identical), macaque STAM (99% identical), rabbit STAM (96% identical), dog STAM (96% identical), guinea pig STAM (93% identical), mouse Stam (92% identical), rat Stam (91% identical), pig STAM (84% identical), tropical clawed frog stam (77% identical), zebrafish stam (72% identical), Drosophila melanogaster Stam (44% identical), Caenorhabditis elegans stam-1 (29% identical), and 3 more. Paralogues in human: STAM2 (55% identical), HGS (28% identical), TOM1L2 (22% identical), TOM1 (19% identical), GGA1 (17% identical), GGA3 (16% identical), TOM1L1 (14% identical), GGA2 (13% identical), WDFY1 (8% identical), WDFY2 (8% identical).
Diseases named in the same sentence as STAM in open-access papers:
STAM is named in the same sentence as 23 diseases in open-access papers, as found by Europe PMC text mining. Sharing a sentence is not in itself a finding about the gene and the disease. The quoted sentences say what the papers report.
autoimmune disease (3 papers, 2020 to 2025). A disorder resulting from loss of function or tissue destruction of an organ or multiple organs, arising from humoral or cellular immune responses of the individual to their own tissue constituents. "Interestingly, changes in sTAM levels are not consistent when comparing different arthritis related autoimmune diseases." (PMID 32964059, 2020). "Enhanced levels of sTAM in biological fluids are not restricted to SLE, RA, MS, and other autoimmune disorders such as Sjogren’s syndrome or Behcet’s disease." (PMID 40044635, 2025).
vitiligo (2 papers, 2025 to 2026). Generalized well circumscribed patches of leukoderma that are generally distributed over symmetric body locations and is due to autoimmune destruction of melanocytes. "The specific expression of STAM in Treg cells allowed us to define a novel STAM+ Treg subset in vitiligo, which may contribute to disease development." (PMID 41438750, 2025). "Here, we identified 13 cell subsets and found that, compared with those in healthy individuals, Treg cells in progressive vitiligo patients are more abundant and express genes such as RTKN2, IKZF2, IL2RA, and STAM." (PMID 41438750, 2025). "Notably, the STAM gene has not been previously reported in Treg cells, suggesting that it may play a significant role in Treg regulation in vitiligo." (PMID 41438750, 2025).
Behcet disease (1 paper, 2025). A chronic, relapsing, multisystemic vasculitis characterized by mucocutaneous lesions, as well as articular, vascular, ocular and central nervous system manifestations. "Enhanced levels of sTAM have been reported in several autoimmune affections: systemic lupus erythematosus, rheumatoid arthritis, Sjogren's syndrome, or Behcet's disease." (PMID 40596706, 2025).
COVID-19 (1 paper, 2022). A disease caused by infection with severe acute respiratory syndrome coronavirus 2. "Here, four hub genes including MVB12A, CHMP6, STAM, and VPS37B were considered to be involved in the core regulation of autophagy in severe COVID-19 cases." (PMID 35923698, 2022). "Therefore, MVB12A, CHMP6, STAM, and VPS37B were regarded as hub genes regulating autophagy in severe COVID-19." (PMID 35923698, 2022).
hepatocellular carcinoma (1 paper, 2023). A malignant tumor that arises from hepatocytes. "We constructed the prognostic risk score for patients with hepatocellular carcinoma as follows: risk score = (0.3519) × PPM1G + (0.0637) × FKBP1A + (0.0673) × STAM + (0.0373) × MAD2L2 + (0.0031) × TBL1XR1 + (0.0172) × ANXA5." (PMID 38049741, 2023). "Plate cloning and CCK8 experiments showed that the inhibition of STAM, ANXA5, and M2D2L2 expression significantly reduced the clonal formation and proliferation of hepatoma cells compared to the control group." (PMID 38049741, 2023).
liver cancer (1 paper, 2023). An epithelial or non-epithelial malignant neoplasm that arises from the liver. "The present study demonstrated that the expression levels of ANXA5, MAD2L2, and STAM in liver cancer cell lines were significantly higher than those in normal hepatocytes." (PMID 38049741, 2023). "The results revealed higher expression levels of STAM, ANXA5, and MAD2L2 in liver cancer cell lines compared to normal hepatocytes." (PMID 38049741, 2023). "In addition, in liver cancer cell lines MHCC97H, MHCC97L, and HCCLM3, which exhibited relatively high expression levels, we knocked down STAM, ANXA5, and MAD2L2 using siRNA and observed alterations in the biological functions of HCC cells." (PMID 38049741, 2023).
liver cirrhosis (1 paper, 2025). "Elevated sTAM levels are also found in patients with type 2 diabetic nephropathy and liver cirrhosis." (PMID 40596706, 2025).
ovarian carcinoma (1 paper, 2023). A malignant neoplasm originating from the surface ovarian epithelium. "The downregulation of exosomal miR-145-5p in ovarian cancer cells improved ovarian cancer development, and its exosome target STAM was identified." (PMID 37569824, 2023).
tumor (7 papers, 2021 to 2025). "Loss of Hrs, ESCRT-0 subunit STAM1 (Signal Transducing Adaptor Molecule) and Tsg-101 all reduce exosome secretion in multiple cell types such as tumor and dendritic cells." (PMID 33892745, 2021). "This is in accord with the reported presence of sTAM in the conditioned media of tumour cells in the culture." (PMID 40044635, 2025). "Therefore, the association between the high levels of sTAM and IBD-associated cancer can be explained by their decoy function leading to the formation of tumour-supporting inflammatory environment." (PMID 40044635, 2025). "Low-molecular-weight compounds that inhibit the dimerization of HGS/C and STAM/C, such as HGS/C and OP12-462, are expected to exhibit tumor growth inhibitory effects." (PMID 39859488, 2025). "In our study, 10q11.23 (PRKG1), 10q22.1 (CSTF2T), 10p12.33 (MRC1), and 10p12.1 (STAM) occurred in 37.5% of ChRCC and not in RO, indicating the potential of the two cytobands in differentiating the two tumours." (PMID 39684226, 2024).
cancer (6 papers, 2020 to 2025). A tumor composed of atypical neoplastic, often pleomorphic cells that invade other tissues. "Surprisingly, enhanced levels of sTAM are detectable in biological fluids of cancer patients as well." (PMID 40044635, 2025).
infection (1 paper, 2015). The state of being infected such as from the introduction of a foreign agent such as serum, vaccine, antigenic substance or organism. "Our finding that transcription of mRNA of STAM may be regulated by lncRNA opens a new approach to study the pathogenesis of sPTB and PPROM through the connection between UPS and infection-inflammation pathways." (PMID 25884766, 2015).
STAM also shares sentences with these, for which no sentence is quoted: Arthritis (1 paper); brain neoplasm (1); Clear Cell Renal Cell Carcinoma (1); ependymoma (1); keratoconus (1); lymph node metastasis (1); prostate carcinoma (1); rheumatoid arthritis (1); Sjogren syndrome (1); systemic lupus erythematosus (1); type 2 diabetic nephropathy (1); viral infection (1).